BMP2 (bone morphogenetic protein 2)
Diseases named in the same sentence as BMP2 in open-access papers (continued):
Sharing a sentence is not in itself a finding about the gene and the disease.
benign ovarian tumors (1 paper, 2010). "Semi-quantitative RT-PCR and western blot were applied to detect the expression of BMP-2 and its receptors BMPRIA, BMPRIB, and BMPRII in EOC, benign ovarian tumors, and normal ovarian tissue at the mRNA and protein levels." (PMID 20587070, 2010).
Brain atrophy (1 paper, 2026). Partial or complete wasting (loss) of brain tissue that was once present. "Minimal in vivo bone regeneration was observed for all hydrogel groups; however, BMP-2 microsphere addition fortuitously reduced motor skill impairment and brain atrophy." (PMID 41758528, 2026).
Cachexia (1 paper, 2022). Severe weight loss, wasting of muscle, loss of appetite, and general debility related to a chronic disease. "We also observed a clear decrease in genes dominantly regulating fat cell differentiation, including CEBPB, CEBPD, BMP2, and KLF4, in vPreA in cachexia group, as compared to patients without cachexia." (PMID 36376273, 2022).
cardiac anomalies (1 paper, 2022). "Pathogenic variants in BMP2 are associated with autosomal dominant Short stature, facial dysmorphism, and skeletal anomalies with or without cardiac anomalies 1 (MIM: #617877) and the identified variant has already been reported as causative of this phenotype." (PMID 36360260, 2022).
cardiomyopathy (1 paper, 2023). A disease of the heart muscle or myocardium proper. "The study also showed that Bmp2 acts downstream of Tbx20 in imparting protection against ER stress–induced cardiomyopathy." (PMID 36805334, 2023). "In the current study, we examine the function of Tbx20 and bone morphogenetic protein 2 (Bmp2) signaling during ER stress–induced cardiomyopathy." (PMID 36805334, 2023). "Our study reported an elevated level of Bmp2 protein both during the initial stages as well as prolonged ER stress response in adult murine hearts, thus making it a potential biomarker candidate for early detection of ER stress–mediated cardiomyopathies." (PMID 36805334, 2023). "The role of Tbx20 and Bmp2 signaling during ER stress–mediated cardiomyopathy has not been reported to date." (PMID 36805334, 2023).
cartilage disease (1 paper, 2021). Softening and degeneration of the CARTILAGE. "Thus, our findings reveal that the Bmp2–Runx2–Smoc1/Smoc2 axis plays an important role in bone formation; it may offer novel and effective therapeutic strategies associated with various bone and cartilage diseases." (PMID 34667264, 2021).
cerebral cavernous malformation (1 paper, 2021). A disorder characterized by malformations in the structure of the capillaries in the brain. "Increased BMP6 or BMP2 expression have also been demonstrated in cerebral cavernous malformations and cancer." (PMID 33021694, 2021).
chondromalacia (1 paper, 2012). Pathological processes involving the chondral tissue (cartilage). "Since localizations of chondromalacia (CM) has previously been described as a critical factor for long-term prognosis following treatment of cartilage defects, this parameter was evaluated in this study with regard to a possible different expression of BMPR-1A and BMP-2." (PMID 22272175, 2012).
chronic myelogenous leukemia (1 paper, 2014). "Of note, studies from the Zon laboratory showed BMP2 treatment of K562 and U937 recruited phosphor SMAD1 with lineage specific factors (erythroid factor GATA1 in K562 cells derived from chronic myelogenous leukemia in erythroid blast crisis and CEBPA in U937 myelomonocytic cells)." (PMID 25544748, 2014).
congenital heart malformation (1 paper, 2023). A disease that has its basis in the disruption of heart development. "This is the first study assessing the role of BMP-2 and 4 in congenital heart malformations." (PMID 37627976, 2023).
congenital myasthenic syndrome (1 paper, 2022). Congenital myasthenic syndrome (CMS) is a group of genetic disorders of impaired neuromuscular transmission at the motor endplate characterized by fatigable muscle weakness. "With the exception of the BMP2 gene, only the gene SNAP25 (OMIM#600322), which is related to congenital Myasthenic syndrome 18, has been reported in prenatal diagnosis with decreased fetal movements and in utero onset for possible prenatal clinical diagnosis." (PMID 35227291, 2022).
dentin dysplasia type II (1 paper, 2022). Dentin dysplasia type II (DD-II) is a rare mild form of dentin dysplasia (DD) characterized by normal tooth roots but abnormal primary dentition. "Mice lacking Bmp-2 (Osx-Cre;Bmp-2fx/fx, Collα1-Cre;Bmp-2fx/fx, Wnt1-Cre-;Bmp-2) exhibit dentinogenesis imperfecta type II and type III (DGI-II, DGI-III), and dentin dysplasia type II (DD-II)." (PMID 35883659, 2022).
diabetic retinopathy (1 paper, 2022). "Previous studies have identified several candidate genes associated with the progression of diabetic retinopathy; examples of such candidate genes that were selected in our studies and found to be associated with diabetic retinopathy are GRB2, GHRHR, BMP2, and GAPDH." (PMID 36360284, 2022).
diffuse midline glioma (1 paper, 2024). A diffuse glioma that arises from the midline structures of the central nervous system. "Combined tumor-autonomous BMP2/BMP7 expression drives a quiescent-invasive tumor cell state in pediatric diffuse midline gliomas (pDMG)." (PMID 39373720, 2024).
emphysema (1 paper, 2021). "Using this method, 14 new selection loci for resistance and susceptibility to gastrointestinal nematodes have been found in sheep, the gene ABHD2 related to emphysema and the gene BMP2 related to the bone morphology and body type of animals." (PMID 33708236, 2021).
esophageal cancer (1 paper, 2016). A primary or metastatic malignant neoplasm involving the esophagus. "Despite that recombinant human bone morphogenetic protein-2 (rhBMP-2) has been reported as a stimulatory effecter of cancer cell growth because of its characteristic like morphogen, the biological functions of rhBMP-2 in human esophageal cancer cells are unknown." (PMID 27230238, 2016).
femoral head osteonecrosis (1 paper, 2012). "In the experimental group, BMP-2 mRNA expression in femoral head osteonecrosis both with and without lateral decompression showed a decreasing trend with the increased time of post-operation." (PMID 22876776, 2012). "In contrast, in the experimental group, the expression of BMP-2 protein in the steroid-induced femoral head osteonecrosis with and without lateral decompression both showed a progressively decreasing trend with the increased post-operation time." (PMID 22876776, 2012).
fibrodysplasia ossificans progressiva (1 paper, 2018). Fibrodysplasia ossificans progressiva (FOP) is a severely disabling heritable disorder of connective tissue characterized by congenital malformations of the great toes and progressive heterotopic ossification that forms qualitatively normal bone in characteristic extraskeletal sites. "Previous studies have demonstrated the osteoinductive effects of BMP2 within skeletal muscle, and links are present between BMP‐induced ectopic bone formation and a rare genetic form of HO termed fibrodysplasia ossificans progressiva (FOP)." (PMID 27696748, 2018).
fibrous dysplasia (1 paper, 2012). A genetic, non-inheritable disorder caused by osteoblastic differentiation defects that result in the replacement of bone marrow and trabecular bone by fibrous stroma and immature bone. "Fibrous dysplasia and non-fibrous dysplasia subjects could be clearly separated by differences in the expression of BMP2, BMP4, BMPR1A, BMPR2, and other members of the BMP pathway." (PMID 23230423, 2012).
fluorosis (1 paper, 2024). "The Col1a1, Bcl2, Fgfr1, Mmp9, Mmp13, Bmp2, and Bmp7 genes are the key regulatory factors in fluorosis bone metabolism." (PMID 39125380, 2024).
folate deficiency (1 paper, 2015). A nutritional condition produced by a deficiency of FOLIC ACID in the diet. "However, we proposed that impaired decidualization of the endometrium by folate deficiency may contribute to fetal abnormalities, as previous studies have shown that BMP2, a well-known marker of decidualization, plays an important role in cephalic neural tube closure." (PMID 25781218, 2015).
hair loss (1 paper, 2023). "The YH complex effectively inhibited the expressions of BMP-2 and TGF-β in the skin of depilated hair loss mice." (PMID 37998718, 2023).
hearing loss (1 paper, 2023). "We concluded that the POU4F3 variations might regulate Wnt, Notch, and/or BMP pathways, specifically leading to the misregulation of BMP2, MYO6, and AHI1 in the pathogenesis of hearing loss." (PMID 37537203, 2023).
Hepatic steatosis (1 paper, 2022). Steatosis is a term used to denote lipid accumulation within hepatocytes. "Therefore, we sought to explore whether BMP2 could be related to NAFLD by assessing the expression of BMP2 in liver and serum from patients with biopsy-proven NAFLD as well as in an in vitro model of hepatic steatosis." (PMID 35614516, 2022).
Hepatitis (1 paper, 2015). Inflammation of the liver. "The oral bLf administration in the hepatitis mouse model up regulated the activity of anti-inflammatory factors including IL-11 and bone morphogenetic protein 2 (BMP2)." (PMID 26016555, 2015).
hepatitis C infection (1 paper, 2012). "During active hepatitis C infection, the HCV core protein induces over-expression of BMP2, which then participates in the activation of hepatic stellate cells and also functions to suppress hepatocyte proliferation in response to liver damage." (PMID 23667740, 2012).
hepatoblastoma (1 paper, 2023). Hepatoblastoma (HB) is a malignant hepatic tumor and is the most common pediatric liver cancer. "Pathway enrichment analysis showed that the essential genes are similarly enriched with class 2 hepatoblastoma genes, targets of BMP2, DREAM complex, MYC and β-catenin, and all these pathways are commonly shared by the ABC-Myc cell lines." (PMID 37414763, 2023). "Pathway enrichment analysis of the essential genes using the ‘Genetic and Chemical Perturbation database’51 showed that they are enriched in class 2 hepatoblastoma genes (CAIRO_HEPATOBLASTOMA_CLASSES_UP, n = 612), and are targets of BMP2, DREAM complex, MYC and β-catenin." (PMID 37414763, 2023).
HIV-1 infection (1 paper, 2020). The type species of lentivirus and the etiologic agent of acquired immunodeficiency syndrome (AIDS). "This study addressed perturbations in systemic levels of diverse TGF-β superfamily members (TGF-β1, activins A and B and BMP-2) during the critical initial stages of HIV-1 infection and at time-points during subacute and chronic infection." (PMID 33329587, 2020). "There was a mild elevation in systemic BMP-2 concentration in acute HIV-1 infection at 9 to 12 days post-T0." (PMID 33329587, 2020). "Notably, no substantial systemic elevation of activin A, activin B or BMP-2 was observed at any stage of HIV-1 infection, although there was a trend for higher circulating levels of activins A and B at later stages of infection." (PMID 33329587, 2020).
hydronephrosis (1 paper, 2012). Collection of urine in the renal pelvis that results in dilatation of the renal pelvis and calyces. "In fact, expressions of Bmp signaling genes (e.g., BMP2, BMP7 and BMPRIA) are reported to be decreased in the fibrotic renal tissue of human hydronephrosis." (PMID 22860096, 2012).
Hypercholesterolemia (1 paper, 2018). An increased concentration of cholesterol in the blood. "A previous study reported that there is evidence to suggest that statins, which have been safely used for treatment of hypercholesterolemia, enhance the biosynthesis of BMP-2." (PMID 30002343, 2018).
Hyperkeratosis (1 paper, 2020). Hyperkeratosis is a histopathological term defining a thickened stratum corneum and may be present in many different skin conditions, with many possible overlaps. "A more recent report has shown that overexpression of constitutively active BMP-receptor-IB (one of the receptors for BMP2) in transgenic mice leads to ichthyosis-vulgaris-like skin disorder characterized by hyperkeratosis." (PMID 33028365, 2020).
hypophosphatemia (1 paper, 2010). Lower than normal levels of phosphates in the circulating blood. "The initiation of hypophosphatemia just prior to or after the fracture in our model would circumvent this potential impairment of BMP2 action on progenitor cells, thus leading to a less severe phenotype than that observed in the mice where BMP2 is ablated from the limbs during embryonic development." (PMID 19839770, 2010). "Despite the BMP2 resistance we observed, and in contrast to mice lacking BMP2 in their limbs, the recruitment of cells during the inflammatory phase of fracture repair was not profoundly impaired by hypophosphatemia." (PMID 19839770, 2010).
IgA nephropathy (1 paper, 2024). "We found that BMP2, COL4A3, and COL4A4 were not upregulated either in other glomerular cells in PMN or in podocytes/HRMCs in IgA nephropathy." (PMID 38785168, 2024).
infarction (1 paper, 2020). A localised pathological necrosis of tissue resulting from obstruction of the blood supply usually by a thrombus, an embolus, or vascular torsion. "The findings of multivariate analysis support the involvement of BMP-2 in the development of post-infarction LVR." (PMID 32992577, 2020). "This can indirectly indicate that BMP-2 is more actively involved in the early post-infarction myocardial remodeling." (PMID 32992577, 2020).
inflammatory bone diseases (1 paper, 2021). "In addition, suppression of gut microbiota translocation ameliorates vascular calcification through inhibition of toll-like receptor (TLR) 9-mediated BMP-2 expression, which ameliorates inflammatory bone diseases via suppression of the TLR9/NF-κB/BMP-2 signaling pathway." (PMID 34176870, 2021).
intrauterine growth restriction (1 paper, 2014). "Of the many BMP ligands and receptors, Bmp2, Bmpr2 and Acvr1 have been previously shown to play important roles in endometrial function, with both early implantation (Bmp2 and Acvr1) and mid-gestational (Bmpr2) defects, some reminiscent of human intrauterine growth restriction." (PMID 24945252, 2014).
iron metabolism disorders (1 paper, 2024). "In conclusion, the findings regarding this BMP2 gene variant not only underline its relevance to iron metabolism disorders but also provide valuable insights for future research in this field." (PMID 39599580, 2024).
ischemic stroke (1 paper, 2025). A stroke disorder caused by obstruction of blood flow to the brain, due to thrombotic (local blood clot formation) or embolic (due to a blood clot or other material traveling from another site) event. "Recent research has demonstrated that extracellular matrix protein-3 (ECM3) binded to extracellular Bmp2 reduces astrocyte-mediated neuroinflammation by inhibiting the BMP signaling pathway, thereby exerting a neuroprotective effect against ischemic stroke." (PMID 41213924, 2025).
keloid (1 paper, 2025). An irregularly shaped, elevated mark on the skin caused by deposits of excessive amounts of collagen during wound healing. "This downregulation in normal fibroblasts was also found to increase expression of collagens via the BMP2 pathway, potentially contributing to keloid formation." (PMID 40835838, 2025).
lung squamous cell carcinomas (1 paper, 2022). "In addition to BMP7, a separate study also found that activation of the BMP2/4-BMPR signaling pathway conferred resistance to epidermal growth factor receptor tyrosine kinase inhibitors (EGFR-TKIs) in patients with lung squamous cell carcinoma harboring mutations in the EGFR gene." (PMID 36353620, 2022). "Another group found that BMP2/4-BMPR-SMAD1/570S6K activation promoted resistance to erlotinib, an EGFR-TKI, in lung squamous cell carcinomas with EGFR mutations." (PMID 36353620, 2022).
malignant glioma (1 paper, 2012). A grade III or grade IV glioma arising from the central nervous system. "We examined the mRNA and protein expressions of BMP2, BMPR-II, BMPR-IA, BMPR-IB and Smad1/5/8 in normal astrocytes and malignant glioma cell lines using real-time RT-PCR and western blot analysis, respectively." (PMID 22650359, 2012).
mammary adenocarcinoma (1 paper, 2016). "Mouse mammary adenocarcinoma cells (4T1) on 3D collagen-glycosaminoglycan scaffolds with or without BMP-2." (PMID 27027241, 2016).
melorheostosis (1 paper, 2023). Melorheostosis is a rare connective tissue disorder characterized by a sclerosing bone dysplasia, usually limited to one side of the body (rarely bilateral), that manifests with pain, stiffness, joint contractures and deformities. "The study found that there was increased expression of certain proteins, including transforming growth factor beta (TGF-β), bone morphogenetic protein 2 (BMP-2), and insulin-like growth factor 1 (IGF-1) in the bone tissues of melorheostosis patients compared to healthy controls." (PMID 37241101, 2023).
meningioma (1 paper, 2019). A generally slow growing tumor attached to the dura mater. "BMP2/4 expression was examined in early passage human primary meningioma cells and was found to be expressed in a majority of these cells; however, the role of BMP signaling in meningioma tumors is still not known." (PMID 31039818, 2019).
myocardial ischemia (1 paper, 2023). A disorder of cardiac function caused by insufficient blood flow to the muscle tissue of the heart. "Due to the increasing evidence of the regulatory roles of BMP2 in angiogenesis and CM functionality, interest in utilizing BMP2 as a treatment for CAD and the underlying myocardial ischemia has emerged." (PMID 38028463, 2023). "For example, in an acute myocardial ischemia model of an injured neonatal mouse, BMP2 induced endocardial angiogenesis." (PMID 38028463, 2023). "In another study, systemic delivery of recombinant BMP2 protein shortly after MI limited CM apoptosis without affecting the heart functionality in an acute myocardial ischemia model in adult mice." (PMID 38028463, 2023). "Although not usable as an intramyocardial GT for treating myocardial ischemia due to induced inflammation and pericardial effusion, BMP2 may benefit cell therapies that induce cardiac regeneration after MI." (PMID 38028463, 2023).
myositis (1 paper, 2021). "In humans, the BMP2 gene is located on chromosome 20 and is considered an excellent candidate for fibrodysplasia (myositis)." (PMID 34780475, 2021).
nasal polyps (1 paper, 2021). "In 2001, a rare presentation of osseous metaplasia in nasal polyps was reported, and endogenous BMP-2 expression was shown to be present through immunostaining." (PMID 35463995, 2021).
nasopharyngitis (1 paper, 2017). An inflammatory process that affects the nasopharynx. "The mRNA level of BMP2 was evaluated in 22 NPC tissues and 14 non-cancerous nasopharyngitis (NP) tissues by qRT-PCR." (PMID 28455969, 2017).
neck fractures (1 paper, 2020). "Therefore we established a new protocol for closed reduction and internal fixation (CRIF) using cannulated screws combined with bone morphogenetic protein 2 (BMP-2) composite materials to treat acute femoral neck fractures." (PMID 32028406, 2020).